OR4K17 (olfactory receptor family 4 subfamily K member 17)
Description:
Odorant receptor.
Synonyms: OR14-29
Tractability: Small molecule: it belongs to a druggable protein family. Antibody: UniProt places it where antibodies can reach, with medium confidence; UniProt predicts a signal peptide or a membrane-spanning region; its Gene Ontology location is reachable by antibodies, with medium confidence.
Gene: Protein-coding gene on chromosome 14 (20,110,739 to 20,122,199, forward strand). Ensembl gene ENSG00000176230.
Subcellular location: Cell membrane
Pathways (Reactome):
Sensory Perception: Expression and translocation of olfactory receptors
Gene Ontology:
Molecular function: olfactory receptor activity; G protein-coupled receptor activity
Biological process: detection of chemical stimulus involved in sensory perception of smell; G protein-coupled receptor signaling pathway
Cellular component: plasma membrane; membrane
Genetic constraint (gnomAD): Missense variants: 472 observed, 377.35 expected, observed/expected ratio (o/e) 1.25, 90% interval 1.16 to 1.35. Synonymous variants: 155 observed, 137.28 expected, observed/expected ratio (o/e) 1.13, 90% interval 0.99 to 1.29.
Homologues: Orthologues: macaque OR4K17 (97% identical), chimpanzee OR4K17 (96% identical), rabbit OR4K17 (84% identical), pig OR4K17 (65% identical). Paralogues in human: OR4K15 (62% identical), OR4K14 (60% identical), OR4K5 (60% identical), OR4K1 (59% identical), OR4K13 (58% identical), OR4K2 (57% identical), OR4F5 (56% identical), OR4F4 (56% identical), OR4L1 (56% identical), OR4F17 (55% identical), OR4F6 (54% identical), OR4F16 (53% identical), and 116 more.
Diseases named in the same sentence as OR4K17 in open-access papers:
OR4K17 is named in the same sentence as 1 disease in open-access papers, as found by Europe PMC text mining. Sharing a sentence is not in itself a finding about the gene and the disease. The quoted sentences say what the papers report.
autoimmune thyroiditis (1 paper, 2025). "Patients with increased I exposure experience hypomethylation of most of the CpG locus of RAB8A, olfactory receptor family 4 subfamily K member 17 (OR4K17), and RAP1A, indicating that excess I is involved in the pathogenesis of autoimmune thyroiditis." (PMID 39940256, 2025).